CCR8 (C-C motif chemokine receptor 8)
Diseases named in the same sentence as CCR8 in open-access papers (continued):
Sharing a sentence is not in itself a finding about the gene and the disease.
Hypertension (2 papers, 2019 to 2022). The presence of chronic increased pressure in the systemic arterial system. "It suggests that CCR8 may be a new biomarker related to hypertension and insulin resistance, and is a new target for the treatment of human cardiovascular diseases." (PMID 36246058, 2022). "However, the role and mechanism of CCR8 in hypertension and insulin resistance are still unclear and need to be further explored." (PMID 36246058, 2022). "CCR8 may be a new biomarker related to hypertension and insulin resistance and is a new target for the treatment of human cardiovascular diseases." (PMID 36246058, 2022).
lung adenocarcinoma (2 papers, 2021 to 2022). A carcinoma that arises from the lung and is characterized by the presence of malignant glandular epithelial cells. "We found that gene related T cell and antigen-presenting cell (APC) were significantly reduced in CCR8-high tumors compared with levels in CCR8-low tumors in both lung adenocarcinoma and lung squamous cell carcinoma." (PMID 35354899, 2022).
metastatic diseases (2 papers, 2015 to 2016). "In this study, we analyzed the expression of intratumoral CCR8 and the impact of CCR8 expression on recurrence-free survival (RFS) in a large cohort of ccRCC patients without synchronous metastatic diseases." (PMID 26716905, 2016).
metastatic melanoma (2 papers, 2015 to 2025). A melanoma that has spread from its primary site to another anatomic site. "This study showed that blocking CCR8 or CCL1 inhibits tumor cell migration to lymphatic endothelial cells and that CCR8 is also expressed in human metastatic melanoma." (PMID 25853550, 2015).
multiple sclerosis (2 papers, 2018 to 2021). A progressive autoimmune disorder affecting the central nervous system resulting in demyelination. "The CCR8–CCL1 interaction is suspected of playing a role in CCR8 expression changes in diseases such as multiple sclerosis." (PMID 34500609, 2021).
neuropathy (2 papers, 2023 to 2025). A disorder affecting the nervous system that manifests with pain, tingling, numbness, and/or muscle weakness. "CCR8, a receptor protein necessary for pronociceptive CCL1, did not increase in STZ-induced animals, implying that the turnover of CCR8 may be increased in neuropathy." (PMID 41169500, 2025). "Moreover, CCL1/CCR8 signaling is suggested to be important for the development of neuropathic pain, since the spinal upregulation of CCL1 was demonstrated in STZ-, CCI- and PSNL-induced neuropathy." (PMID 37570736, 2023). "Another ligand that binds to CCR8 is CCL18; however, it is not present in mice and rats, and thus far, its role in neuropathy in patients needs to be studied." (PMID 37570736, 2023).
ovarian carcinoma (2 papers, 2022 to 2023). A malignant neoplasm originating from the surface ovarian epithelium. "The proportion and phenotypic characteristics of CD4+CCR8+ Tregs in peripheral blood of healthy individuals, peripheral blood of OC patients and OC tissues were clarified as well as the effect of ovarian cancer microenvironment on CD4+CCR8+ Tregs recruitment." (PMID 37950246, 2023). "Chemotactic assays in vitro suggested that high level of CCL1 and CCL18 in the TME of ovarian cancer contributed to the increased infiltration of CD4+CCR8+ Tregs into tumor tissues." (PMID 37950246, 2023). "In the TME of ovarian cancer, CCR8 was the dominant chemokine receptor expressed on CD4+ TILs which was closely related to the pathological process of ovarian cancer." (PMID 37950246, 2023). "Therefore, we believe that the high expression of CCL1 and CCL18 in ovarian cancer TME is an important factor in the increase of CD4+CCR8+ Tregs infiltration into tumor tissues." (PMID 37950246, 2023). "The expression level of CCR8 in infiltrating CD4+ T cells of ovarian cancer tissue was significantly higher than that in peripheral blood of healthy controls and ovarian cancer patients, and high expression of CCR8 was significantly correlated with advanced tumor stage and poor differentiation." (PMID 37950246, 2023). "However, the current research on CCR8 in the immune microenvironment of ovarian cancer has not been clear." (PMID 37950246, 2023).
parasite infection (2 papers, 2021 to 2022). "In this context, the C-C motif chemokine receptor 8 (CCR8) was shown to be a critical regulator of ILC2s during parasitic infections and allergic lung diseases." (PMID 34177944, 2021).
skin infection (2 papers, 2015 to 2022). An inflammatory process affecting the skin, caused by bacteria, viruses, parasites, or fungi. "However, the absence of CCR8 did not influence the recruitment of T cells against skin infection, indicating that CCR8 may be more essential in the homeostasis in the skin." (PMID 35096274, 2022).
viral infection (2 papers, 2012 to 2018). "Of note, murine skin memory T cells also express CCR8 transcripts in response to viral infections." (PMID 29427415, 2018). "In this study we found that CCR5 and several other chemokine receptors which support viral infection, such as CCR8 and CXCR6 are either absent or demonstrate markedly different expression levels in macrophage-like cell lines compared with primary AMs." (PMID 23102269, 2012).
abortion (1 paper, 2025). the ending of pregnancy by removing a fetus or embryo before it can survive outside the uterus. "The critical role of CCR8+ dTregs in maintaining maternal-fetal immune tolerance during early pregnancy is evidenced by the ability of adoptively transferred CCR8+ dTregs to rescue fetal loss in abortion-prone mice." (PMID 41368646, 2025).
adult T-cell leukemia/lymphoma (1 paper, 2022). A peripheral (mature) T-cell neoplasm linked to the human T-cell leukemia virus type 1 (HTLV-1), adult T-cell leukemia/lymphoma is endemic in several regions of the world, in particular Japan, the Caribbean, and parts of Central Africa. "Here, we found that both adult T-cell leukemia/lymphoma (ATLL) patients and ATLL cells had increased CCR8 expression but did not express CD7." (PMID 35693763, 2022).
AIDS (1 paper, 2011). A syndrome resulting from the acquired deficiency of cellular immunity caused by the human immunodeficiency virus (HIV). "In addition to the known CCR5 and CCR2 associations, significant associations were identified for CCR3, CCR8, and CCRL2 on progression to AIDS." (PMID 22046140, 2011). "Significant associations with differential progression to clinical AIDS were observed for CCR3 -255C (RH = 0.62, P = 0.009), for CCRL2-243V (RH = 0.66, P = 0.03), and for CCRL2-167F (RH = 1.89, P = 0.0003) and for CCR8-27G (RH = 1.44, P = 0.004)." (PMID 22046140, 2011). "Genotypes of exonic polymorphisms in chemokine coreceptor genes CCR3, CCRL2 and CXCR6 on Chromosome 3p21 and in CCR8 and CX3CR1 on 3p22 were tested for their genetic influence on AIDS progression." (PMID 22046140, 2011).
allergic asthma (1 paper, 2019). A asthma with a basis in a pathological type I hypersensitivity reaction. "The potential of CCR8 antagonists has been considered to treat allergic asthma, since several studies have shown a role for CCR8 in the recruitment of Th2 cells and in the development of inflammation in murine models of allergic asthma." (PMID 31270368, 2019). "Diverse roles for CCR8 in allergic asthma have been reported so far: e.g., involvement in the development of systemic Th2-type immune response and migration of Th2 cells, or regulatory T-cells, into the inflamed airway tissues." (PMID 31270368, 2019). "Based on these studies, the potential of CCR8 antagonists to treat allergic asthma has been discussed." (PMID 31270368, 2019). "However, the importance of CCR8 in allergic asthma has been debated, since additional studies have shown a dispensable role of CCR8 in the recruitment of Th2 cells into inflamed respiratory tissues of experimental mice." (PMID 31270368, 2019). "The potential of CCR8 antagonists to treat allergic asthma has been discussed." (PMID 31270368, 2019). "Several studies showed an essential role of the CCR8/CCL1 axis in the recruitment of Th2 cells and the development of inflammation in murine models of allergic asthma or atopic dermatitis." (PMID 31270368, 2019).
autoimmune disease (1 paper, 2024). A disorder resulting from loss of function or tissue destruction of an organ or multiple organs, arising from humoral or cellular immune responses of the individual to their own tissue constituents. "Human chemokine receptor 8 (CCR8) is a promising drug target for immunotherapy of cancer and autoimmune diseases." (PMID 38721308, 2024). "CCR8 is a promising drug target for immunotherapy of cancer and autoimmune diseases." (PMID 38721308, 2024).
autoimmune gastritis (1 paper, 2025). Inflammation of the body fundic mucosa of the stomach. "Autoantibody responses and autoimmune gastritis were observed in mice 13 days after systemic Treg depletion but not in mice treated with anti-CCR8 antibody that depleted Tregs in tumor tissues." (PMID 40053558, 2025).
brain injury (1 paper, 2024). Acute and chronic (see also brain INJURIES, CHRONIC) injuries to the brain, including the cerebral hemispheres, CEREBELLUM, and brain STEM. "However, it is still necessary to test whether and how blocking CCR6 and CCR8 affects the activities of their endogenous ligands, which are known to be upregulated, as is well documented for CCL1 and CCL20 after nerve and brain injury, respectively." (PMID 38612597, 2024).
chronic obstructive pulmonary disease (1 paper, 2014). A chronic and progressive lung disorder characterized by the loss of elasticity of the bronchial tree and the air sacs, destruction of the air sacs wall, thickening of the bronchial wall, and mucous accumulation in the bronchial tree. "Although CCL1 is not the primary chemokine secreted into the peritoneal cavity during laparotomy in humans, inflammatory macrophages in lung tissue from patients with chronic obstructive pulmonary disease (COPD) express high levels of CCR8." (PMID 24714157, 2014).
clear-cell renal cell carcinoma (1 paper, 2016). "To assess the clinical association between CCR8 expression and the risk of post-surgery recurrence in patients with clear-cell renal cell carcinoma (ccRCC), we detected intratumoral CCR8 expression in 472 post-nephrectomy ccRCC patients retrospectively enrolled." (PMID 26716905, 2016).
COVID-19 (1 paper, 2023). A disease caused by infection with severe acute respiratory syndrome coronavirus 2. "In addition, we find that fibroblasts in COVID-19 lung adventitial niches express the chemokine receptor CCR8." (PMID 36774347, 2023). "However, while these stromal cells were the main subset expressing CCR8 in COVID-19 lungs, the CCR7 signal was not restricted to the stromal compartment." (PMID 36774347, 2023).
Crohn disease (1 paper, 2020). A gastrointestinal disorder characterized by chronic inflammation involving all layers of the intestinal wall, noncaseating granulomas affecting the intestinal wall and regional lymph nodes, and transmural fibrosis. "In initial expression studies, CCR8 expression was upregulated in the intestinal mucosa of patients with ulcerative colitis and to a lesser extend Crohn’s disease compared to controls as evidenced by qPCR analysis of total RNA of gut tissue specimens." (PMID 33613532, 2020).
cutaneous T-cell lymphoma (1 paper, 2023). "Since CCR8 was shown to be expressed by tumor cells in cutaneous T-cell lymphoma and by tumor-infiltrating Tregs in tumors, targeting CCR8-expressing cells may be a useful strategy to treat cutaneous T-cell lymphoma." (PMID 36765704, 2023). "In this study, they analyzed the peripheral blood of 13 patients with SS and persistent blood involvement and found that Sézary cells in the blood of cutaneous T-cell lymphoma patients express higher levels of the homing marker CCR8 compared to healthy controls’ T cells." (PMID 36765704, 2023). "The chemokines CCL8 and CCL18, which are known to bind CCR8, were found to be highly expressed in the skin of cutaneous T-cell lymphoma patients and may play a role in the homing of CCR8-expressing lymphocytes to the skin in these patients." (PMID 36765704, 2023).
diabetics (1 paper, 2022). "The results revealed that CCR8 was highly expressed in diabetics and Ang II-induced VSMCs." (PMID 36246058, 2022).
fracture (1 paper, 2024). "Both in human patients with bone fracture and a mouse model of bone injury, we identified a bone injury–responding Treg subpopulation with bone-repair capacity marked by CCR8." (PMID 39509336, 2024). "Here, combined with scRNA-Seq of BM Tregs in fracture patients and bulk-RNA-Seq of Tregs isolated from mouse injured femur tissue, we found that a bone-injury–responding Treg population marked by CCR8 displayed a distinct tissue-repair phenotype." (PMID 39509336, 2024).
injury (1 paper, 2025). Damage inflicted on the body as the direct or indirect result of an external force, with or without disruption of structural continuity. "In conclusion, we report a novel CCR8-antagonizing peptide that inhibited CCL1-driven intrahepatic monocytes infiltration and differentiation into pro-inflammatory phenotype, consequently ameliorating liver inflammation and fibrogenesis in an acute liver injury mouse model." (PMID 40486848, 2025).
Insulin resistance (1 paper, 2022). Increased resistance towards insulin, that is, diminished effectiveness of insulin in reducing blood glucose levels. "Here, we investigated the role of CCR8 in Ang II-induced insulin resistance in VSMCs." (PMID 36246058, 2022).
Kaposi's sarcoma (1 paper, 2016). A malignant neoplasm characterized by a vascular proliferation which usually contains blunt endothelial cells. "Furthermore, evidence rose that endothelial-derived spindle cells of human Kaposi sarcoma acquire chemotaxis through its intrinsic CCR8 expression." (PMID 26716905, 2016).
liver inflammation (1 paper, 2025). "In conclusion, in this study, we report a design, molecular characterization and therapeutic investigation of a CCR8 antagonizing peptide AP8ii that inhibited monocyte-macrophage chemotaxis in vitro and ameliorated MoMFs infiltration, liver inflammation and early fibrosis in vivo." (PMID 40486848, 2025).
malaria (1 paper, 2019). Malaria is a serious and sometimes fatal disease caused by a parasite that commonly infects a certain type of mosquito which feeds on humans. "The present study shows the subordinate expression pattern of chemokine receptors CXCR3 and CCR8 in response to increased malaria burden, it exemplifies the reduced trafficking of TH1, CD8+T cells, NK cells, monocytes and TH2 cells within lymphoid organ or in the peripheral tissues." (PMID 31614626, 2019).
malignant glioma (1 paper, 2012). A grade III or grade IV glioma arising from the central nervous system. "CCL1-mediated Ca2+i mobilization through CCR8 has been described in cells expressing the receptor endogenously, e.g. monocytes, HL-60 clone 15, IL-2-activated natural killer cells, T cell lines, BW5147 cells, and U87 malignant glioma cells." (PMID 22479563, 2012).
MALT lymphoma (1 paper, 2015). An indolent, extranodal type of non-Hodgkin lymphoma composed of small B-lymphocytes (centrocyte-like cells). "In comparing gastric to extragastric MALT lymphomas, the upregulation of CXCR1 and CXCR2 accompanied by downregulation of CCR8 and CX3CR1 and loss of XCR1 expression in extragastric MALT lymphomas appear to be key determinants for the site of origin of MALT lymphomagenesis." (PMID 25922601, 2015).
myocarditis (1 paper, 2012). Myocarditis is a condition that is characterized by inflammation of the heart muscle (myocardium). "CXCL9 mRNA expression directly correlated with the intensity of myocarditis, as well as with mRNA expression of CXCR3, CCR4, CCR5, CCR7, CCR8 and their ligands." (PMID 23150742, 2012).
ovarian tumor (1 paper, 2023). "CD4+CCR8+ Tregs are the main type of infiltrating CD4+ Tregs in ovarian tumor tissues, which have stronger immunosuppressive phenotypes, secrete more inhibitory cytokines and have stronger proliferation ability." (PMID 37950246, 2023). "In addition, we found that ovarian tumor tissue culture supernatant had a more significant chemotactic effect on CD4+CCR8+ Tregs, suggesting that some components of the culture supernatant were involved in recruitment." (PMID 37950246, 2023).
Pain (1 paper, 2023). An unpleasant sensory and emotional experience associated with actual or potential tissue damage, or described in terms of such damage. "Also, oral administration of RAP-103, a peptide inhibitor of CCR8, fully prevents mechanical allodynia and inhibits the development of thermal hyperalgesia after SNL, suggesting the involvement of CCR8 in the initiation and maintenance of nerve injury-induced neuropathic pain." (PMID 36376699, 2023).
pancreatic cancer (1 paper, 2024). "Our previous study showed that CCR8+ Tregs were highly infiltrative and had a stronger immunosuppressive ability than CCR8− Tregs in pancreatic cancer." (PMID 37935468, 2024). "According to our previous study, CCR8 was specifically expressed in activated tumour-infiltrating suppressive Tregs in pancreatic cancer." (PMID 37935468, 2024).
psoriasis (1 paper, 2023). An autoimmune condition characterized by red, well-delineated plaques with silvery scales that are usually on the extensor surfaces and scalp. "In addition, CCR8 and CCR6 were described for their role in atopic skin diseases and psoriasis, respectively." (PMID 37371632, 2023).
renal cell carcinoma (1 paper, 2015). "Studies have shown that MDSCs from patients with urothelial and renal cell carcinoma express CCR8 (the CCL1 receptor), and tumor-derived CCL1 promotes the accumulation of MDSCs in both the peripheral blood and tumor tissue." (PMID 26470881, 2015).
sarcoma (1 paper, 2022). A usually aggressive malignant neoplasm of the soft tissue or bone. "Furthermore, we reveal five targetable antigens (C16orf54, CCR8, CYTIP, SAMD3 and TBX21) by identifying modules associated with the sarcoma immune landscape." (PMID 36153483, 2022). "Furthermore, this study identified specific molecules (C16orf54, CCR8, CYTIP, SAMD3 and TBX21) that can be used as predictors of the risk of progression and therapeutic targets for patients with sarcomas." (PMID 36153483, 2022).
sialadenitis (1 paper, 2021). Sialadenitis is an infection of the salivary glands. "In conclusion, we have demonstrated that upregulation of the mCCL8 (analog of hCCL18)–CCR8 axis in LAT mice could play a crucial role in fibrosis via ERK1/2 pathway-dependent type-I collagen production, as well as in cell infiltration in sialadenitis." (PMID 34391459, 2021).
Sjögren’s syndrome (1 paper, 2021). "In our previous studies, we revealed that the chemokine (C-C motif) ligand 18 (CCL18) and its receptor chemokine (C-C motif) receptor 8 (CCR8) in labial salivary glands (LSGs) of IgG4-RD patients are upregulated when compared with those of healthy controls and of Sjögren’s syndrome patients." (PMID 34391459, 2021).
status epilepticus (1 paper, 2016). Status epilepticus is defined as a continuous seizure lasting more than 30 min, or two or more seizures without full recovery of consciousness between any of them. "Of these three chemokines, only CCR8 might participate in neuroinflammation because it has been suggested to play a significant role in the pathogenesis of chronic relapsing experimental autoimmune encephalomyelitis and pilocarpine-induced status epilepticus." (PMID 27635404, 2016).
vasculitis (1 paper, 2020). "In PR3-ANCA vasculitis, levels of TNF-α, thromboxane A2 (TXA2) and CD14 were increased, while in MPO-ANCA vasculitis the C-C motif chemokine receptor 8 (CCR8) levels was higher and IL-10 expression was lower compared to controls." (PMID 33023023, 2020).